IL6 (interleukin 6)
Diseases named in the same sentence as IL6 in open-access papers (continued):
Sharing a sentence is not in itself a finding about the gene and the disease.
Insulin resistance (continued). "Interleukin 6 (IL-6) is another inflammatory cytokine, strongly correlated with insulin resistance in the liver through JNK and via increasing the expression of SOCS3." (PMID 30096951, 2018). "IL-6 is known to be secreted by macrophages and DC during NAFLD, and has been associated with increased risk for insulin resistance in men." (PMID 30405618, 2018). "This promotes insulin resistance and impaired glucose tolerance through altered secretion of adipokines and other inflammatory markers such as interleukin 6, 8, 10 and macrophage chemotactic protein-1." (PMID 30627515, 2018). "It is also well documented that the release of inflammatory cytokines, such as tumor necrosis factor-α (TNF-α) and interleukin-6 (IL-6), which are often cited as crucial cytokines that mediate insulin resistance, can be induced by chronic stress." (PMID 29433422, 2018). "IL-6 induced insulin resistance and insulin secretion dysfunction by promoting lipid oxidation and participates in promoting the occurrence and development of DN." (PMID 30210570, 2018). "Prior studies in PLHIV in the US and Europe have linked soluble inflammatory mediators (e.g., C-reactive protein (CRP) and interleukin-6 (IL-6)) to insulin resistance or incident DM." (PMID 30009182, 2018). "A low C-HDL, and high levels of NEFA, triglycerides, IL-6, TNF-α and CRP have been previously implicated in the development of insulin resistance." (PMID 30400254, 2018). "PPARβ/δ activation prevents IL-6-induced insulin resistance by inhibiting the signal transducer and activator of transcription 3 (STAT3) pathway in adipocytes, whereas this pathway is over activated in PPARβ/δ-null mice compared to wild-type animals." (PMID 29558390, 2018). "In type 2 diabetic rats, the treatment with ASE reduced blood glucose, insulin resistance, leptin and IL-6 levels, lipid profile, and vascular dysfunction." (PMID 29920546, 2018). "Inflammatory cytokines, including IL‐1 and IL‐6, are released from macrophages and adipocytes and lead to the pathogenesis of insulin resistance and development of type 2 diabetes mellitus." (PMID 30258609, 2018). "IL-6 has been described as a proinflammatory cytokine that contributes to the development of insulin resistance in skeletal muscle." (PMID 30356272, 2018). "An increase in the number of M1 macrophages within adipose tissue in MetS can result in higher secretion of IL-6 from adipose tissue, and consequently lead to insulin resistance." (PMID 30383538, 2018). "The stimulation of NF-κB increased the levels of downstream inflammatory factors such as TNF-α, IL-1β, and IL-6, which promoted the insulin resistance in the liver." (PMID 30453687, 2018). "Animal and human models have demonstrated innate immunity as well as experimental in vivo induction of inflammation via bolus of an inflammatory cytokine such as TNF-α or IL-6, results in release of adipokines and generation of peripheral insulin resistance." (PMID 29910818, 2018). "According to this recent study, short-term PPARβ/δ activation prevents IL-6-induced insulin resistance as a result of PPARβ/δ forming a complex with nuclear TCPTP45 and retaining it in the nucleus, thereby deactivating the STAT3-SOCS3 signalling." (PMID 29558390, 2018). "Pan-blocking of IL-6 signaling using an anti-IL-6 antibody (MR16-1) has been shown to ameliorate insulin resistance and reduce liver-fat accumulation in high-fat diet-fed mice." (PMID 29868016, 2018). "IL-6 is a potent cytokine that plays a significant role in the pathogenesis of insulin resistance and type 2 diabetes." (PMID 30425746, 2018). "Inflammatory cytokines such as TNF-α and IL-6 promote the development of insulin resistance, and a recent study has reported that anti-inflammation agents showed efficacy in reducing blood glucose level." (PMID 30453687, 2018).
Insulin resistance (continued). "It was also found that serum progranulin contributes to developing insulin resistance through increasing IL-6, which in turn, impairs insulin signaling by stimulating SOCS3 expression." (PMID 30096951, 2018). "This shift leads to a relative decrease of anti-inflammatory IL-4, IL-10, and IL-13 and to an increased production of TNF-α, IL-1β, IL-6 in the adipose tissue, which altogether promote tissue and systemic inflammation and insulin resistance." (PMID 30558209, 2018). "Pro-inflammatory cytokines such as IL-6 and TNF-α up-regulate the expression of the suppressor of cytokine signaling 3 (SOCS3) implicated in inflammation-mediated insulin resistance in the liver and adipocytes." (PMID 30360409, 2018). "Plasma levels of hepcidin, IL-6, Serum Insulin and ferritin using ELISA method, serum iron levels using a spectrophotometric method, and Insulin resistance by using HOMA were measured in the two groups of PCOS (case group) and healthy subjects (control group)." (PMID 31239849, 2018). "For example, various agents including TNF-α, Interleukin-1 (IL-1), IL-6, free fatty acids, dexamethasone, and high insulin were used to make models of insulin resistance in 3T3-L1 adipocytes." (PMID 30445954, 2018). "Pro-inflammatory cytokines such as tumor necrosis factor α (TNFα), interleukin-6 (IL-6), and resistin can promote insulin resistance that can, in turn, be ameliorated by a decrease in visceral adipose tissue." (PMID 29141990, 2018). "In the liver, IL-6 induces insulin resistance by activating STAT3-suppressor of cytokine signalling 3 (SOCS3) pathway." (PMID 29558390, 2018). "LP increases serum TNF-α and IL-6 concentrations and induces insulin resistance while ADN has anti-inflammatory properties and decreases the release of proinflammatory mediators." (PMID 30246011, 2018). "The non-significant association between IL-6 and DI after adjustment for change in insulin sensitivity is consistent with prior reports that IL-6 contributes to the development of insulin resistance." (PMID 30102726, 2018). "Several studies have shown that TNFa and IL-6 are involved in the development of insulin resistance and blocking of TNF-alpha activity with TNFa antagonists results in improved insulin sensitivity." (PMID 29954107, 2018). "The contribution of miR-301a to the IL-6-induced insulin resistance has been demonstrated to be due to a direct effect on the PTEN expression." (PMID 29535681, 2018). "Other studies have shown that weight loss after gastroplasty progresseswith decreased circulating levels of interleukin-6 and CRP in association withimproved insulin resistance." (PMID 30539977, 2018). "Interleukin (IL)-6 is one of the inflammatory mediators released by adipose tissue that correlates most strongly with obesity and insulin resistance, predicting the development of type 2 diabetes mellitus." (PMID 29558390, 2018). "Chronic exposure to elevated IL-6 and CRP levels is associated with the development of insulin resistance, the metabolic syndrome, and Type 2 Diabetes." (PMID 29704817, 2018). "Eventually, increased serum levels of PAI-1, ET- 1, tumor necrosis factor-α (TNF-α), interleukin-6 (IL-6), and C-reactive protein (CRP), reflect association of insulin resistance with low-grade inflammation and endothelial dysfunction." (PMID 30170601, 2018). "Patients and cows with NASH displayed high blood NEFAs, TNF‐α and IL‐6 concentrations, mitochondrial dysfunction and insulin resistance." (PMID 29602237, 2018). "Inflammatory cytokines, including TNF-α and IL-6, are thought to contribute to the development of insulin resistance through the activation of several stress kinases, such as JNK." (PMID 29433422, 2018). "Complementary to this, hepatocyte-specific IL6R, IL6, or STAT3 deficient mice develop increased gluconeogenesis and insulin resistance, as a result of G6pc upregulation, likely via a PI3K/FoxO1-independent pathway, as well as age-related obesity and steatosis." (PMID 30374109, 2018).
Insulin resistance (continued). "The mice also showed increased levels of pro-inflammatory cytokines, such as interleukin-6 and tumor necrosis factors, which favor the development of insulin resistance." (PMID 30400886, 2018). "Third, reduction in the duration of sleep leads to elevation of the levels of cortisol, IL-6, and TNFα, resulting in activation of the sympathetic nervous system that promotes insulin resistance." (PMID 29364963, 2018). "Cytokines such as TNFa and IL-6 favor insulin resistance in RA patients, as well as a more atherogenic lipid profile." (PMID 29954107, 2018). "MAP4K4 downregulation in T cells results in enhancement of the IL-6+ Th17 cell population, leading to insulin resistance and T2D in both human and mice." (PMID 28061846, 2017). "PDX mimics the effect of physical exercise by stimulating the secretion of IL-6 from skeletal muscle and thereby attenuates insulin resistance and hepatic gluconeogenesis." (PMID 28469249, 2017). "Meanwhile, interleukin (IL)-1β and IL-6 production and secretion are induced by hypoxia in adipocytes, which are known to trigger systemic and local insulin resistance." (PMID 28353649, 2017). "IL-6 leads to increased insulin resistance by blocking the IRS-mediated insulin signaling in hepatocytes and muscle cells causing impaired insulin-stimulated glucose uptake into muscle cells." (PMID 28555043, 2017). "Studies have shown that inflammatory factors such as TNF-α, IL-6, and monocyte chemoattractant protein-1 (MCP-1) interfere with the insulin signal transduction pathway and cause insulin resistance." (PMID 29164155, 2017). "Expression of miR-378 was found to be significantly elevated after TNF-α, IL-6, and leptin stimulation, whose result indicates that miR-378 probably is a novel mediator in the molecular mechanisms related to insulin resistance and obesity." (PMID 29077020, 2017). "High fructose diet induces insulin resistance in skeletal muscle, with nuclear translocation of NF-κB 65, and subsequent secretion of IL-6, which is known to be mostly released from skeletal muscle." (PMID 28353649, 2017). "IL-17 and fatty acids can synergistically stimulate hepatic cells to secrete IL-6, and IL-6 aggravates insulin resistance." (PMID 28646856, 2017). "TNF-α, IL-6 and IL-1β, all pro-inflammatory markers, are overproduced in fatty liver and participate in the development of insulin resistance and activate hepatic macrophages called Kupffer cells." (PMID 28555043, 2017). "Alantolactone pretreatment showed a protective effect against chronic IL-6 treatment and increased glucose uptake level, suggesting its potential activity on glucose intolerance and insulin resistance." (PMID 28706484, 2017). "For example, high levels of TNF-α, interleukin-6, and interleukin-8 have all been reported in various diabetic and insulin-resistant state." (PMID 29387832, 2017). "The pro-inflammatory cytokine, Interleukin-6 (IL-6), has been proposed to be one of the mediators that link chronic inflammation to glucose intolerance and insulin resistance." (PMID 28706484, 2017). "TNF-α and IL-6 are considered the major players in chronic low-grade inflammation and insulin resistance." (PMID 28396851, 2017). "KAP transgenic were protected from hfd-induced insulin resistance, increased blood pressure and exhibited lower IL-6 serum levels and diminished expression of inflammatory markers in the adipose." (PMID 29170528, 2017). "There is strong evidence that a persistent inflammatory state, as occurs in hemodialysis patients, interferes with normal insulin signaling and inflammatory markers as interleukin 6 and C-reactive protein correlated with insulin resistance in clinical trials." (PMID 28719612, 2017). "On the other hand, IL-6 signaling specifically in hepatocytes protects the animals from hepatic inflammation and insulin resistance." (PMID 28661458, 2017).
Insulin resistance (continued). "In the present study, we observed protective effects of alantolactone, a sesquiterpene lactone isolated from Inula helenium against glucose intolerance and insulin resistance induced by prolonged exposure of IL-6." (PMID 28706484, 2017). "Specifically, short-term treatment with IL-6, improved glucose control and insulin sensitivity, whereas long-term treatment with IL-6 contributed to glucose intolerance and insulin resistance." (PMID 28706484, 2017). "On the other hand, type 2 DM is due to increased peripheral insulin resistance secondary to enhanced production of IL-6 and TNF-α in response to high-fat and/or calorie-rich diet (rich in saturated and trans fats)." (PMID 28824543, 2017). "IL-6 is also reported to induce insulin resistance by blocking PI3K and AKT pathway and impair glycogen synthesis by downregulating microRNA200s and upregulating friend of GATA 2 (FOG-2)." (PMID 28706484, 2017). "The frequencies of IL-6-producing T cells are correlated with the value of insulin resistance index." (PMID 28061846, 2017). "MAP4K4 deficiency has been reported to stabilize TRAF2 and induce TRAF2/IL-6 upregulation, leading to insulin resistance." (PMID 28101327, 2017). "Systemic neutralization of IL6 also exhibits a significant improvement in insulin resistance in mice." (PMID 28085064, 2017). "The proinflammatory factors derived from macrophages (TNF-α, IL-1 β, IL-6) are related to the development of insulin resistance." (PMID 29077020, 2017). "The upregulation of inflammatory cytokines (mainly tumour necrosis factor (TNF)-α and IL-6) and their role in insulin resistance has been established and in this connection, readers are directed to the various review articles on the subject." (PMID 29023424, 2017). "Though IL-6 is supposed to contribute to hepatic insulin resistance, its levels are similar in cirrhotic patients with normal and high HOMA-IR." (PMID 28661458, 2017). "The macrophages in adipose cells secrete proinflammatory cytokines (adipocytokines) such as C-reactive protein, interleukin (IL)–6, IL-8, IL-10, and tumor necrosis factor–α; these cytokines impair insulin signaling, inducing insulin resistance." (PMID 28234943, 2017). "Here we report that classical IL-6 signalling in T cells promotes inflammation and insulin resistance during the first 8 weeks on a high-fat diet (HFD), but becomes dispensable at later stages (after 16 weeks)." (PMID 28466852, 2017). "BBR inhibited inflammation, ameliorated insulin resistance, and reduced the production of proinflammatory cytokines such as IL-6, IL-17, TNF-α, and interferon-γ (IFNγ) in NOD mice." (PMID 29164155, 2017). "HsCRP is primarily activated by other cytokines in the liver and IL-6 is elevated under the circumstance of insulin resistance and visceral obesity." (PMID 28951620, 2017). "Elevated blood viscosity decreases the perfusion of skeletal muscle, leading to myocyte expression of the myokine IL-6, decreased glucose uptake, insulin resistance, hyperglycemia, and metabolic syndrome." (PMID 29435395, 2017). "The JNK and IKK-β pathways are activated by ROS and various other factors including the inflammatory cytokines such as TNF-α, IL-6, and IL-1beta which are involved in the development of insulin resistance found in type 2 diabetes." (PMID 27034691, 2016). "IL-6 is a proinflammatory cytokine that correlates with postoperative insulin resistance and the magnitude of (surgical) trauma and increases hours after the hit." (PMID 26880899, 2016). "In the same context, MIF stimulates the inflammatory adipocytokines; resistin and IL-6 both are key molecules in the development of insulin resistance." (PMID 27298517, 2016). "Circulating IL-6 stimulates the hypothalamic-pituitary-adrenal (HPA) axis, activation of which is associated with central obesity, hypertension, and insulin resistance." (PMID 26942201, 2016).
Insulin resistance (continued). "Serum levels of these cytokines correlate remarkably well with the presence of insulin resistance, and adipose tissue-derived TNF-α and IL-6 have been shown to regulate hepatic insulin resistance via upregulation of SOCS3, a suppressor of cytokine signaling." (PMID 27247565, 2016). "Several inflammatory cytokines including TNF-a, IL-1b, and IL-6 have been identified as being involved in the development of insulin resistance." (PMID 27525022, 2016). "Model 2 shows that presence of insulin resistance was positively associated with MCP-1 (OR = 1.005, p = 0.024) and IL-6 levels; and, negatively associated with CRP levels (OR = 0.989, p = 0.049)." (PMID 26862350, 2016). "Leptin overexpression was found responsible for TNF-α and IL-6-related chronic inflammation, insulin resistance, liver fibrosis, and HCC development." (PMID 27703473, 2016). "BAT-derived IL-1α and in particular IL-6 are critical pro-inflammatory cytokines in the induction of insulin resistance and activation of the immune system." (PMID 26795216, 2016). "TNF-α and other pro-inflammatory cytokines including interleukin-6 (IL-6), interleukin-1 β (IL-1β), and C-reactive protein are involved in low-grade chronic inflammation and insulin resistance." (PMID 27092490, 2016). "A multiple linear regression analysis showed both plasma CTRP-3 and HMGB-1 concentrations were independently associated with homeostasis model assessment for insulin resistance (HOMA-IR) and interleukin-6 (IL-6) (P < 0.05 for all)." (PMID 27738641, 2016). "Tumour necrosis factor alpha, IL‐1 and IL‐6 can induce systemic inflammation and insulin resistance." (PMID 26843513, 2016). "Later, other proinflammatory cytokines such as interleukin 1 beta (IL1b) and interleukin 6 (IL6) have been found to induce insulin resistance in experimental settings." (PMID 26751381, 2016). "Offspring of dams exposed to high systemic levels of TNF-α or IL-6 showed increased body weight and adiposity, and exposure to IL-6 alone resulted in insulin resistance in female offspring." (PMID 26858656, 2016). "During pregnancy, IL-6 secretion has been proposed to aggravate insulin resistance and participates in the pathogenesis of GDM." (PMID 27313878, 2016). "For example, IL-10 has been shown to prevent diet-induced insulin resistance, and IL-6 and TNF are known to decrease levels of the protective adipokine adiponectin." (PMID 27148273, 2016). "IL-6 was selected as a prime candidate based on previous studies suggesting that chronic exposure of mice to IL-6 induces insulin resistance in skeletal muscle cells and hepatocytes." (PMID 27342408, 2016). "In the liver, AngII promotes insulin resistance, de novo lipogenesis, and pro-inflammatory cytokine production such as interleukin-6 (IL-6) and tumor growth factor-β (TGF-β)." (PMID 27089331, 2016). "IL-6 promotes insulin resistance in liver cells and negatively regulates insulin signaling and glucose metabolism in adipocytes." (PMID 27313878, 2016). "For example, in the case of muscle, IL-6 promotes muscle catabolism and insulin resistance with chronic IL-6 administration inducing muscle atrophy." (PMID 26941738, 2016). "IL-6 also plays a direct role in insulin resistance by inhibiting insulin receptor signal transduction and insulin action in hepatocytes." (PMID 27213439, 2016). "The GDM animal model showed signs of insulin resistance where expressions of both proinflammatory cytokines (IL-6 and TNF-α), PCK-1, and serum CRP level were higher than control." (PMID 27379252, 2016). "Free fatty acid can also serve as an endogenous signal to stimulate the production of pro-inflammatory mediators, such as TNF-α and IL-6, and inhibition of pro-inflammatory signaling pathways can prevent free fatty acid-induced insulin resistance." (PMID 27213439, 2016).